GLP1R (glucagon like peptide 1 receptor)
Diseases named in the same sentence as GLP1R in open-access papers (continued):
Sharing a sentence is not in itself a finding about the gene and the disease.
Obesity (continued). "Protection from diet-induced obesity is paradoxically also observed in some studies with GLP-1R deficient mice." (PMID 40024571, 2025). "Patients with obesity treated with Glucagon-like peptide-1 receptor agonists (GLP-1 RAs) are associated with improved cardiac and endothelial function." (PMID 40807063, 2025). "Glucagon-like peptide-1 receptor (GLP-1R) agonists are a class of drugs that target incretin hormone action and have shown great efficacy in treating obesity by promoting weight loss." (PMID 39402302, 2024). "Taken together, there is little doubt that interesting times lie ahead for GIPR agonism and antagonism, either alone or when combined with GLP-1R agonists, as a therapeutic intervention for the management of obesity and associated metabolic disease." (PMID 38861364, 2024). "The findings to date indicate that GEP44 is a promising drug targeting limitations associated with current GLP-1R agonist medications for the treatment of obesity and/or T2DM." (PMID 39104812, 2024). "Blocking PVNGLP-1R→DVC synaptic release or ablation of GLP-1R in the presynaptic compartment increases food intake and causes obesity, elevated blood glucose, and impaired insulin sensitivity." (PMID 38559032, 2024). "These retrospective studies suggest a conceivable role for GLP-1R agonists in chemoprevention, particularly for high-risk individuals, such as those with obesity and/or T2D." (PMID 39931650, 2024). "Among these, NNC0090-2746 and tirzepatide showed improved efficacy in terms of EE, insulin sensitivity and weight loss, as compared to single GLP-1R agonism in a model of diet-induced obesity." (PMID 37378828, 2023). "Yet, during continuous and longer exposure to a CAF diet over 15 days before the development of obesity, only central activation of GLP1R reduced intake and caused weight loss." (PMID 37293487, 2023). "In animal models of obesity, the administration of this dual GLP-1R/GCGR agonists resulted in better weight loss, lower glucose levels, and reduced food intake, compared to pure GLP-1r agonists alone." (PMID 36767008, 2023). "Second-generation anti-obesity medications glucagon-like peptide-1 receptor agonists (GLP-1RAs) cause weight loss and improve body composition by reducing visceral and ectopic fat depots of WAT, resulting in improved cardiometabolic health." (PMID 37239935, 2023). "These therapies and interventions include obesity reduction by weight loss and bariatric surgery, antidiabetic agents (particularly GLP-1R agonists and SGLT2 inhibitors), and statin therapy." (PMID 37900360, 2023). "Semaglutide is a GLP-1R single agonist, similar to tirzepatide, that significantly improves hyperglycemia and obesity and has been approved by the FDA in 2021 as a weight loss drug for chronic weight management." (PMID 37096236, 2023). "This has led to detailed characterization of the involvement of GLP‐1 in physiological and pathophysiological mechanisms which underlie the use of GLP‐1R agonists as anti‐diabetic and anti‐obesity agents." (PMID 35523760, 2022). "Research showed that GLP1R single nucleotide variants (SNVs) rs2268641 and rs6923761 are associated with obesity and anthropometric measurements." (PMID 36339410, 2022). "Among the most promising agents in this respect are the glucagon‐like 1 receptor (GLP‐1R) agonists that have been extensively studied in obesity and T2DM and induce both weight loss and improved glycaemic control." (PMID 34156126, 2021). "Flavonifractor is associated with several diseases, such as obesity, atrial fibrillation, coronary artery disease, and medications (antidiabetic drugs, such as Metformin and Glucagon-like peptide 1 Receptor agonist)." (PMID 33809103, 2021). "GLP-1R agonists are associated with significant long-term weight loss and are very rapidly gaining popularity for the treatment of obesity." (PMID 34867786, 2021).
Obesity (continued). "Recently, new pharmacologic therapeutics targeting the glucagon-like peptide-1 receptor such as semaglutide are promising for weight loss in adults with obesity or overweight." (PMID 33928108, 2021). "In this field, ALT-801 emerged as a novel peptide-based dual GLP-1R/GCGR agonist designed by AltImmune to treat the obesity and metabolic dysfunction caused by NASH." (PMID 34195230, 2021). "GLP-1R SNPs have been confirmed in the association with obesity, pancreatic beta-cell function, and T2DM in different populations." (PMID 30271789, 2018). "This study suggested that Lira alleviated HFD-induced kidney injury at least partly via directly restoring renal metabolism, thus GLP-1R agonist is a promising therapy for obesity-associated CKD." (PMID 29590132, 2018). "Liraglutide, a glucagon-like peptide-1 receptor (GLP-1R) agonist currently used for the treatment of obesity-associated type 2 DM, confers minimum risk of hypoglycemia and promotes weight loss." (PMID 29110715, 2017). "GLP-1R neuron ablation in the DMH caused obesity and increased food intake in rats." (PMID 41542773, 2026). "Moreover, recent data indicate that GLP-1R agonist treatment restores the functionally defective natural killer (NKT) cells in people living with obesity, independently of its weight loss effect." (PMID 40892365, 2025). "Finally, for combined GIPR/GLP1R agonism, lower BMI through dual receptor activation resulted in a substantial reduction in obesity risk, with highly concordant estimates across datasets." (PMID 40931165, 2025). "For GLP1R agonism, genetically proxied lower BMI by GLP1R variants was consistently associated with a reduced risk of obesity, with relationships observed for GLP1R agonism in the MVP BMI replication data and a directionally consistent, though less precise, estimate in the primary BMI GWAS data." (PMID 40931165, 2025). "The support of endocrinologists specialized in the management of pharmacological treatment of obesity should be requested, as emerging evidence shows the benefits of glucagon-like peptide-1 receptor agonist for managing insulin resistance associated with polycystic ovary syndrome." (PMID 39903407, 2025). "While FLOW excluded participants < 18 years of age, it is likely GLP-1R agonists and other weight modification medications will play some role in the future management of children with obesity that is unresponsive to lifestyle measures and causing complications such as hypertension or diabetes." (PMID 38806767, 2024). "GLP1 receptor (GLP1R) agonists reduced appetite and induced weight loss in humans with obesity." (PMID 38732142, 2024). "Targeted therapy for weight loss, such as glucagon-like peptide-1 receptor (GLP1R) agonists, may also help us to understand the role of obesity in asthma." (PMID 39200943, 2024). "This meta-analysis provides robust evidence that bariatric metabolic surgery significantly reduces both major adverse cardiovascular events (MACE) and all-cause mortality compared to glucagon-like peptide-1 receptor agonists (GLP-1RAs) in patients with obesity." (PMID 39552962, 2024). "Disruption of synaptic transmission or ablation of GLP-1R in this circuit causes obesity." (PMID 38559032, 2024). "The utility and translation of these interventions for humans may be difficult for prospective mothers with obesity, thus the use of pre-pregnancy therapeutic weight loss aids, such as glucagon-like peptide-1 receptor agonists, is also discussed." (PMID 37432265, 2023). "In addition, clinical trials of tirzepatide, a dual GIP/GLP-1R agonist, have reported a weight loss of up to 20%, providing new hope that obesity and its related co-morbidities can be managed with medication rather than surgical interventions." (PMID 36834794, 2023). "Interestingly, in vivo and retrospective studies show that anti-diabetic drugs, including metformin and GLP-1R agonists, have great potential in treating obesity-associated asthma." (PMID 37893170, 2023).
Obesity (continued). "In the GLP1R gene, we found variants associated with dyslipidemia, resistance to liraglutide and exenatide, metabolic syndrome, insulin levels, BMI, glucose levels, and obesity, according to previously studies." (PMID 37888112, 2023). "However,single agonist peptides activating GLP-1R to stimulate insulin secretionalso suppress obesity-linked glucagon release." (PMID 37523325, 2023). "The therapeutic landscape for GPCR as targets of anti-obesity medications has undergone significant changes with the approval of semaglutide, the first peptide glucagon like peptide 1 receptor agonist (GLP-1RA) achieving double digit weight loss (≥10%) and cardiovascular benefits." (PMID 38161982, 2023). "Indeed, the SURMOUNT program including four global trials, showed efficacy of Tirzepatide as a glucagon-like peptide-1 receptor agonist in weight loss in patients with obesity." (PMID 37689633, 2023). "Moreover, genetic association analysis of 30 genes related to obesity using a Bayesian hierarchical generalized linear model found that the rs2268641 gene variant of GLP1R was significantly associated with BMI." (PMID 36339410, 2022). "In addition, the rs2268641 (C>T) SNP of GLP1R was associated with obesity in European Americans, and GIPR SNP rs2334255 (G>T) was identified as a novel common variant associated with both obesity and T2DM risk." (PMID 33503878, 2021). "Genome-wide association studies (GWAS) linked GIPR and GLP1R variants with BMI and obesity." (PMID 33503878, 2021). "Moreover, the postnatal ablation of PVN GLP-1R causes increased food intake, body weight gain, and obesity." (PMID 33126672, 2020). "The natriuretic effect of GLP-1R agonists along with the effects of these drugs on the conventional risk factors for DN (such as hyperglycemia, hypertension and obesity) may represent the most relevant mechanisms underlying their antialbuminuric effect." (PMID 31159279, 2019). "Our findings suggested that GLP-1R agonist is a promising therapy for obesity-associated CKD." (PMID 29590132, 2018). "Interestingly, a recent study has reported that retatrutide, a triple agonist of glucagon receptor (GCGR), glucose-dependent insulinotropic polypeptide receptor (GIPR) and GLP-1R, alleviated tumor growth and chemotherapy resistance in obesity-associated triple-negative breast cancer." (PMID 41244507, 2025). "Defining the cellular targets of GLP-1R therapies in heterogeneous tumors will clarify their preventive or therapeutic mechanisms, which may also intersect with the metabolic and inflammatory pathways linked to obesity." (PMID 41178720, 2025). "Additionally, GLP-1R rs2268641 has been linked to obesity-related traits in European Americans." (PMID 38096145, 2023). "Hence, future studies focusing on further understanding the molecular mechanisms through which obesity augments asthma severity and randomized clinical trials to evaluate the efficacy of metformin and GLP-1R agonists in the treatment of obesity-associated asthma are needed." (PMID 37893170, 2023). "According to the report by Finan, the GLP-1R/GIPR dual-agonists could provide more significant hypoglycemic, hyperlipidemic, and anti-obesity effects compared with single agonists with attenuated gastrointestinal discomfort and nausea (typically associated with GLP-1R agonists)." (PMID 37514148, 2023). "Along with these studies and several additional meta-analyses, it can be concluded that GLP-1R agonists, especially liraglutide and semaglutide, are successful in inducing substantial weight reduction, are well tolerated, and also show signs of improving obesity-related risk factors." (PMID 37510690, 2023). "Since high-fat diet feeding attenuates CCK-induced activation of vagal afferents as well as responses in downstream brain regions, alterations in GLP1R vagal afferent control of meal-related glycemia may also provide a neural mechanism underlying impaired glycemic control in obesity." (PMID 34043943, 2021).
Obesity (continued). "Therefore, GLP-1 has demonstrated a role in renal protection trough modulation of lipid and energy metabolism, and it is supposed that GLP-1R agonists may be a promising therapy in obesity-associated CKD." (PMID 31159279, 2019). "More recently, GLP‐1R agonists have emerged as the primary treatment for obesity and metabolic disorders." (PMID 41151834, 2026). "Glucagon-like peptide (GLP)-1 receptor (GLP1R) agonists exert a multitude of beneficial cardiovascular effects beyond control of blood glucose levels and obesity reduction." (PMID 42123676, 2026). "There has been considerable interest in the potential role of obesity-targeted therapies, such as the glucagon-like peptide-1 receptor agonists and related compounds, in the management of HFpEF." (PMID 41052644, 2026). "Glucagon-like peptide-1 receptor agonists (GLP-1 RAs) have emerged as a less invasive alternative to BS for managing obesity, with recent studies indicating potential benefits for IBD outcomes." (PMID 42117113, 2026). "Background/Objectives: Glucagon-like peptide-1 receptor agonists (GLP-1RAs) are effective treatments for obesity, but substantial weight regain is common after therapy is discontinued." (PMID 41978101, 2026). "This study investigated the protective potential of PHYLN extract loaded into niosomal nanocarriers (PHYLN-NIO) against obesity-induced hepatic steatosis and explored its mechanistic similarity to glucagon-like peptide-1 receptor agonists (GLP-1RAs)." (PMID 42045980, 2026). "Glucagon-like peptide-1 receptor agonists (GLP-1RA) are increasingly used to manage obesity and T2DM." (PMID 42298552, 2026). "Surprisingly, despite the clear anorectic effects of pharmacologically dosed GLP-1, GLP-1R–knockout mice exhibited normal feeding behavior and bodyweight on a chow diet and were protected from high-fat diet–induced obesity." (PMID 41542773, 2026). "Background/Objective: Glucagon-like peptide-1 receptor agonists (GLP-1RAs) have received widespread attention as effective obesity treatments." (PMID 41595322, 2026). "In agreement with the finding that GLP-1R–knockout mice are protected from diet-induced obesity, one group showed that prolonged GLP-1R antagonism using a blocking antibody modestly attenuated weight gain in mice on a high-fat diet." (PMID 41542773, 2026). "Here, we report the design and optimization of novel antibody-peptide conjugates that combine glucose-dependent insulinotropic polypeptide receptor (GIPR) antagonism with glucagon-like peptide 1 (GLP-1) receptor (GLP-1R) agonism for the treatment of obesity." (PMID 41941715, 2026). "GLP-1R mono-agonists on the other hand improve both obesity and CV outcomes with negligible effects on EE." (PMID 41654015, 2026). "There has been a dramatic increase in the use of GLP1R agonists and related "incretins" to treat individuals diagnosed with obesity." (PMID 42095513, 2026). "In this context, glucagon-like peptide-1 receptor agonists (GLP-1 RAs) have emerged as a targeted intervention for the obesity-driven HFpEF phenotype." (PMID 41596526, 2026). "Glucagon-like peptide-1 receptor (GLP-1R) agonists, initially developed for the treatment of type 2 diabetes (T2D) and obesity, have emerged as promising agents with significant cardiovascular benefits beyond glycemic control." (PMID 40243679, 2025). "Given the widespread expression of GLP-1R and the established link between obesity and cancer, there has been a growing interest in the potential for GLP-1R agonists to modulate cancer development and progression." (PMID 41178720, 2025). "Obesity has emerged as a pressing global health challenge, and therapies based on glucagon-like Peptide 1 receptor agonists (GLP-1RAs) have transformed its management." (PMID 41333115, 2025). "In humans, GCG has shown a strong capacity to induce energy expenditure when combined with a single GLP-1R agonist in individuals living with obesity." (PMID 40892365, 2025).
Obesity (continued). "VTADA neuron responsiveness was suppressed during food consumption by semaglutide, a glucagon-like peptide receptor 1 (GLP-1R) agonist anti-obesity drug." (PMID 40146831, 2025). "Due to the widespread use of GLP-1R agonists to treat metabolic dysfunction, obesity, and T2DM, it remains important to understand the systemic physiology of GLP-1R activity." (PMID 40722684, 2025). "Obesity treatment includes bariatric surgery procedures and, more recently, glucagon-like peptide-1 receptor agonists (GLP-1 RAs) for pharmacological management." (PMID 40161879, 2025). "Due to the important role of GLP-1 on glucose and energy metabolism and its short half-life in the circulation, several degradation-resistant GLP-1r agonists have been developed and approved for the treatment of type 2 diabetes and more recently obesity." (PMID 40789661, 2025). "Semaglutide, a glucagon-like peptide-1 receptor agonist, has emerged as a promising pharmacological intervention in obesity management." (PMID 40062102, 2025). "While the advent of GLP-1R agonists have indisputably revolutionized the pharmaceutical intervention of obesity, further improvements in efficacy and tolerability are necessary to maximize the long-term health outcomes of patients." (PMID 40507574, 2025). "Glucagon-like peptide-1 receptor agonists (GLP-1RA) are increasingly utilized for obesity treatment due to their significant metabolic benefits, including weight loss and improved glycemic control." (PMID 41011232, 2025). "Meanwhile, in younger adults with obesity, glucagon-like peptide-1 receptor agonists play a crucial role by improving glycaemia, promoting weight loss, and offering cardiovascular and renal protection." (PMID 40607140, 2025). "While numerous proof-of-concept candidate molecules have been disclosed, the only approved example of multi-receptor agonism for obesity and T2D is the dual GLP-1R/GIPR co-agonist tirzepatide (marketed as Mounjaro® and Zepbound®)." (PMID 39963285, 2025). "Glucagon-like peptide-1 receptor agonists (GLP-1RAs) are increasingly being used to manage obesity in primary care." (PMID 41299124, 2025). "GLP-1R agonists, a typical class B GPCR ligand, lead to significant weight loss in the clinic and are FDA-approved obesity therapies." (PMID 41016636, 2025). "Glucagon-like peptide-1 receptor agonists (GLP-1RAs) are emerging as a promising treatment for obesity but access in primary care is limited." (PMID 40628416, 2025). "GLP1R-based obesity therapies can reduce lean muscle and energy expenditure via adaptive thermogenesis (also known as metabolic adaptation), leading to weight plateaus and regain." (PMID 40961927, 2025). "The glucagon-like peptide-1 receptor agonist (GLP1-RA) semaglutide is a novel treatment for both T2DM and obesity; however, it can be associated with an increased risk of venous thromboembolism (VTE)." (PMID 40792243, 2025). "Glucagon-like peptide-1 receptor agonist (GLP-1RA) pharmaceutical interventions have advanced medical treatment for obesity, yet little is known about nutrient intake while using a GLP-1RA." (PMID 40352260, 2025). "Both hormones also regulate food intake, and the success of GLP1R agonists and dual GLP1R/GIPR agonists in the treatment of obesity has kindled ongoing research to better understand which target cells are most relevant for these pharmacological outcomes." (PMID 39576749, 2025). "While several antiobesity drugs are available, treatment with glucagon-like peptide-1 receptor agonists (GLP-1 RAs) for obesity management appears to be effective for and well tolerated by people with schizophrenia." (PMID 41364787, 2025). "Fortunately, the tide seems to have finally turned, and we are now witnessing an obesity drug revolution with the glucagon-like peptide 1 receptor (GLP-1R) agonist semaglutide spearheading the way." (PMID 39644359, 2025).